YY1 (YY1 transcription factor)
Diseases named in the same sentence as YY1 in open-access papers (continued):
Sharing a sentence is not in itself a finding about the gene and the disease.
glioma (continued). "Subsequently, we performed rescue assays to illustrate how YY1 regulated the process of glioma by modulating SNHG17 expression." (PMID 32009853, 2020). "In glioma stem cells (GSCs) Notch signaling was shown to direct YY1 to repress gene transcription involved in cell differentiation by causing locus specific methylation of histone H3K27." (PMID 33102493, 2020). "In this report it has been shown that miR-218 targets YY1 leading to its downregulation and impaired glioma cell proliferation." (PMID 31824839, 2019). "YY1 expression has been shown to be elevated in glioma tumors and its expression has been attributed to tumor progression." (PMID 31824839, 2019). "They observed a positive correlation between the expression of YY1 and the progression of gliomas and meningiomas and concluded that YY1 would serve as a good potential therapeutic target against brain tumors." (PMID 25053986, 2014). "While high YY1 expressions in lung, breast, and brain and CNS cancers correspond to a high likelihood of cancer metastasis, high expressions of the same YY1 in ovarian cancer increases survival rates." (PMID 25053986, 2014). "Next, we investigated the impact of YY1 on glioma stemness and the role of USP18 in this context." (PMID 40374599, 2025). "The reduced expression of E-cadherin in gliomas may be due, at least in part, to increased YY1 expression and its role in the suppression of E-cadherin." (PMID 38893192, 2024). "The expression of miR-1208 and YY1 was also detected in our 55 glioma clinical samples via qPCR." (PMID 36397164, 2022). "The expression of circPTPRF and YY1 was detected in our 55 glioma clinical samples through qPCR." (PMID 36397164, 2022). "In glioma cell lines, YY1 has been shown to be regulated by the MicroRNA miR-218." (PMID 33102493, 2020). "In gliomas, YY1 is overexpressed and contributes to tumor progression." (PMID 33102493, 2020). "Then, favorable overexpression efficiency of YY1 was obtained in glioma cells." (PMID 32009853, 2020). "Collectively, in glioma, YY1 appears to act as a tumor promoter." (PMID 31824839, 2019). "Given that BA has previously been implicated in blocking diverse canonical YY1/FAS, ERβ, insulin/IGF‐1, MAPK/ERK and Notch signalling pathways in different pathological models, we next investigated which pathway was responsible for UBE2T downregulation in glioma." (PMID 41486508, 2026). "Thus, YY1 regulates the activation of the Wnt1 pathway in glioma cells." (PMID 33728560, 2021). "Interestingly, in glioblastoma multiforme (GBM) the NF-κB family member RelB was shown to interact with YY1 and promote expression of GBM specific genes as well as pro-inflammatory cytokines leading to infiltration of glioma associated macrophages and thus tumor progression." (PMID 31824839, 2019). "Transcripts of VV-GMCSF-Lact-infected glioma and NB cells that directly correlate with CD50 are enriched with mRNAs controlled by transcription factors ATF2, BRCA1, CREB1, ELF1, TAF1, UBTF, and YY1." (PMID 37998351, 2023). "Through literature research, we screened out five mRNAs (SPARC, YY1, ERBB4, MAP3K2, and FZD6) that are highly expressed in glioma tumor tissues and promote glioma progression." (PMID 37554539, 2023). "Furthermore, YY1 could accelerate the growth of glioma via up-regulating SNHG17 expression." (PMID 32009853, 2020). "Recently, we and others demonstrated the role of YY1 on GBM cells and glioma stem cells." (PMID 36059990, 2022).
glioma (continued). "Analysis by iRegulon predicted YY1 (Yin Yang 1) and STAT1 (Signal Transducer and Activator of Transcription) to be possible regulators of a number of proteins that are upregulated in the early grades of glioma." (PMID 34900729, 2021). "The results proved that SNHG17 induced by YY1 facilitated the glioma progression through targeting miR-506-3p/CTNNB1 axis by activation of Wnt/β-catenin signaling pathway, suggesting its potential value as a biomarker in glioma." (PMID 32009853, 2020). "Additionally, YY1 was shown to upregulate transcription of the long non-coding RNA SNHG17, which activates the Wnt/β-catenin signaling pathway and thus contributes to the proliferation of glioma cells and inhibition of apoptosis." (PMID 33102493, 2020).
glioblastoma (27 papers, 2014 to 2025). The most malignant astrocytic tumor (WHO grade IV). "In human cortical astrocytes, YY1 is localized almost exclusively in the cytoplasm, while in glioblastoma cells, YY1 is entirely nuclear." (PMID 39904836, 2025). "CircPTPRF was demonstrated to competitively bind miR-1208 to release Yin Yang 1 (YY1) from translational blocking, elevating the cellular level of this transcriptional repressor in glioblastoma." (PMID 39736850, 2025). "YY1 is a well-known oncogenic transcription factor that has been extensively studied due to its role in glioblastoma progression." (PMID 40374599, 2025). "Recent studies also reported that exos can deliver YY1 siRNA to glioblastoma cells, effectively releasing their payload and enhancing chemotherapy sensitivity." (PMID 40819077, 2025). "Our study underscores the potential of targeting the YY1/USP18/SOX9 axis as a therapeutic strategy for glioblastoma." (PMID 40374599, 2025). "YY1 downregulated by miR-7-5p via direct 3′UTR targeting reduces stemness and enhances temozolomide sensitivity in glioblastoma, positioning the miR-7-5p/YY1 axis as a key regulator of chemoresistance." (PMID 40867514, 2025). "YY1 is expressed in glioblastoma multiforme (GBM) and is involved in its resistance to current therapies." (PMID 38893192, 2024). "In glioblastoma, YY1 acts as an oncogene that stimulates EGFR expression via miRNA effects, in turn, promoting cellular proliferation." (PMID 35999564, 2022). "shRNA-mediated downregulation of YY1 in temozolomide-resistant glioblastoma multiforme cells was shown to compromise the CSC population evaluated based on CD133 expression and spheroid and colony formation assays." (PMID 33728560, 2021). "For example, miR-7 elevated temozolomide-resistant glioblastoma cell sensitivity and repressed stemness via targeting YY1." (PMID 32714093, 2020). "The miR-34a had been shown to target YY1 and the miR-34a-YY1 pathway was demonstrated to regulate expression of epidermal growth factor receptor in glioblastoma multiforme." (PMID 24970812, 2014). "Similarly, in glioblastoma YY1 was found to promote glycolysis and tumor progression through transcriptional activation of G protein subunit Gamma 5 (GNG5)." (PMID 41327312, 2025). "YY1 also interacts with CDK9 in glioblastoma stem cells and maintains stemness." (PMID 40867514, 2025). "For example, in a preclinical study, exosome-based nanoparticles could enhance the efficacy of delivering YY1 inhibitors into glioblastoma cells in both in vitro and in vivo models of the blood–brain barrier (BBB)." (PMID 37444616, 2023). "In glioblastoma CSCs, YY1 mediates self-renewal through regulation of the SENP1/METTL3/MYC axis." (PMID 37444616, 2023). "Notably, miR-7-5p is a negative regulator of YY1, and the levels of miR-7-5p expression were downregulated in temozolomide-resistant glioblastoma cells; thus, miR-7-5p overexpression reversed temozolomide resistance in vivo." (PMID 33728560, 2021). "Specifically, YY1 was overexpressed in cisplatin-resistant glioblastoma cells." (PMID 33728560, 2021). "Similarly, another study showed that YY1 binds to miR-7-5p and increased stemness in glioblastoma cells." (PMID 31956270, 2020). "Also, miR-7-5p levels, which target YY1, are remarkably decreased in temozolomide-resistant glioblastoma cells." (PMID 31861937, 2019). "Additionally, miR-186-5p, which is down-regulated in cisplatin-resistant glioblastoma cells, targets YY1, weakens the sphere formation of glioblastoma cells, and improves the efficacy of chemotherapeutic agents." (PMID 31861937, 2019). "Further evidence indicates that YY1 regulates CSC hallmarks of glioblastoma." (PMID 31861937, 2019). "In glioblastoma (GBM) stem cells, METTL3 and YTHDF2 have been implicated in Yin Yang 1 (YY1)-mediated IFN-β signaling and antigen presentation through m6A methylation, reducing Treg cell infiltration and improving the efficacy of immune checkpoint therapy." (PMID 39987091, 2025).
glioblastoma (continued). "The transcription factor Yin Yang 1 (YY1) plays a pivotal role in the pathogenesis of glioblastoma multiforme (GBM), an aggressive form of brain tumor." (PMID 38893192, 2024). "It has been reported that YY1 was a direct target gene of miR-34a, and enhanced miR-34a expression could reduce cell proliferation, migration and invasion partially by suppressing YY1 expression in glioblastoma multiforme, liver cancer and esophageal squamous cell carcinoma." (PMID 33796457, 2021). "Moreover, miR-7 could increase cell sensitivity to temozolomide and impede cell stemness in temozolomide-resistant glioblastoma cells through downregulating YY1." (PMID 32714093, 2020). "Studies have revealed that YY1 upregulates the expression of CSC markers’ (such as CD133, STAT3, and integrin-α6) expression, thereby promoting the resistance of glioblastoma cells to cisplatin and temozolomide." (PMID 40867514, 2025). "Interestingly, while the YY1-RelA complex was shown to function as a transcriptional repressor, a complex between RelB and YY1 was shown to function as a transcriptional activator in glioblastoma multiforme (GBM) cells and promotes GBM growth." (PMID 31824839, 2019). "Interestingly, YY1 cooperates with HIF-1α to upregulate VEGF expression and facilitate the accumulation of immunosuppressive cells, including MDSCs and regulatory T cells, particularly in glioblastoma." (PMID 40867514, 2025). "YY1 transcriptionally upregulates sentrin/SUMO-specific protease 1 (SENP1) and enhances the methylase activity of methyltransferase-like 3 (METTL3), leading to increased N6-Methyladenosine (m6A)-modification levels in MYC mRNA, which promotes the self-renewal of glioblastoma stem cells (GSCs)." (PMID 37444616, 2023).
cervical carcinoma (26 papers, 2011 to 2025). A carcinoma arising from either the exocervical squamous epithelium or the endocervical glandular epithelium. "YY1 knockdown or motif deletion causing a 70–80% reduction in lnc-FANCI-2 expression in cervical cancer cells." (PMID 40953061, 2025). "Further studies are required to identify the signaling pathways that are regulated by YY1 and to understand the mechanism underlying the action of YY1 during cervical cancer development." (PMID 35408813, 2022). "This study has further, implicated that elevated YY1 levels contributes to drug resistance in cervical cancer." (PMID 31824839, 2019). "However, the E6 promoter of extrachromosomal HPV16 DNA in cervical cancer escaped cellular repression by mutating YY1 target sequences." (PMID 29470526, 2018). "In addition, higher YY1 transcript and protein levels were associated with malignant transformation in cervical cancer, in the presence of a Human Papilloma Virus (HPV) infection." (PMID 21253604, 2011). "Apart from controlling the expression of HPV oncogenes E6 and E7, YY1 is also involved in the regulation of transcriptional activation and repression of many genes associated with multiple cellular processes, and disturbances in these mechanisms can lead to the development of cervical cancer." (PMID 35408813, 2022). "Since HPV infection promotes YY1 expression—leading to elevated lnc-FANCI-2 levels in cervical cancer cells —we next sought to determine how TFAP2 binding and regulatory function vary between normal and HPV-transformed cellular contexts." (PMID 40953061, 2025). "Several studies have investigated the abnormal expression of YY1 in cervical carcinoma and how it contributes to tumor progression." (PMID 41327312, 2025). "PLAU is additionally linked to the movement and infiltration of cells and is controlled by the transcription factor YY1 in cervical cancer." (PMID 38970097, 2024). "In cervical carcinomas, YY1 is overexpressed and is essential in the progression of HPV-infected cervical carcinomas." (PMID 37372319, 2023). "Further studies demonstrated that elevated YY1 levels contributed to drug resistance in cervical cancer patients." (PMID 35408813, 2022). "Several studies have been increasingly conducted worldwide to determine the oncogenic role of YY1 in different cancers other than cervical cancer." (PMID 35408813, 2022). "In cervix cancer, the mutation of glutamate receptor, metabotropic 7 (GRM7) gene can increase the expression of YY1." (PMID 35791393, 2022). "Mechanistically, YY1 plays other key roles in promoting cervical cancer progression by repressing miR-181 and modulating the expression of E-Cadherin and HPV E6 oncoprotein." (PMID 31824839, 2019). "We also found that YY1 was up-regulated in CSCC tissues when compared to normal cervical or CIN I tissue, suggesting a potential relationship between YY1 and the pathogenesis of cervical cancer." (PMID 29470526, 2018). "This study explored abnormal expression of Yin Yang 1 (YY1) in cervical cancer and its correlation with the expression of E-cadherin and human papillomavirus (HPV) 16 E6." (PMID 29470526, 2018). "Studies have also demonstrated up-regulation of YY1 in the cervical cancer, which implicates YY1 overexpression in poor prognosis prediction in cervical cancer." (PMID 29470526, 2018). "YY1 is an important transcription factor that inhibits apoptosis, and it has been shown to be over-expressed in cervical carcinomas." (PMID 25192291, 2014).
cervical carcinoma (continued). "Specifically, treatment of HeLa cells with arsenic trioxide was shown to reduce YY1 expression, which was correlated with increased apoptosis, suggesting that YY1 could be a potential anticancer target for the treatment of cervical carcinoma." (PMID 35408813, 2022). "Interestingly, it has been shown that microRNA-181 (miR-181) targets YY1 expression and inhibits cervical cancer progression, while overexpression of miR-181 inhibits cervical cancer cell growth in vitro and in vivo by regulating YY1 expression." (PMID 35408813, 2022). "Clinical evidence also shown that the decreased expression of miR-29a in high-grade cervical cancer lesions and YY1 and CDK6 as downstream targets of miR-29a may contribute to unchecked cellular proliferation and resistance to apoptotic stimuli in HeLa cells." (PMID 35628336, 2022). "In addition, it was shown that the expression of YY1 in cervical cancers cells is positively correlated with the E6 protein of HPV-16 and negatively correlated with E-cadherin expression." (PMID 35408813, 2022). "DDX5 acts as an oncogene in cervical cancer, which raises the question of whether it exerts its tumor-promoting function by enhancing the oncogenic activity of YY1 or repressing its oncosuppressive role." (PMID 35954483, 2022). "In this regard, we hypothesized that YY1 suppresses the expression of E-cadherin in cervical cancer." (PMID 29470526, 2018). "Our findings may provide new insights into understanding YY1-mediated pathogenesis of cervical cancer." (PMID 29470526, 2018). "However, it is possible that the significantly increased YY1 levels in this cervical carcinoma cell line impede a further raise in target gene expression upon ectopic transfection of the factor, as also reported by others." (PMID 23776572, 2013). "For example, elevated YY1 levels were detected in many tumor types including prostate cancer, ovarian cancer, colon cancer, breast cancer, cervical cancer, osteosarcoma, acute myeloid leukemia, Hodgkin's lymphoma, non-Hodgkin's lymphoma, and follicular lymphoma." (PMID 21253604, 2011). "Thus, it would be worth investigating whether this mechanism plays a role in modulating the functions of DDX3X and YY1 in cervical cancer." (PMID 35954483, 2022). "We particularly/notably emphasize the role of YY1 in the HPV life cycle and cervical cancer development." (PMID 35408813, 2022). "The expression of YY1 is found to be increased in HPV-16- and HPV-18-positive cervical cancer cells." (PMID 35408813, 2022). "In this review, we described the complex role of the YY1 protein in the viral life cycle and cancer development, particularly emphasizing the role of YY1 in the HPV life cycle and cervical cancer development." (PMID 35408813, 2022). "It has been documented that YY1 can bind to the HPV long control region and regulate the expression of viral oncogenes E6 and E7; however, its role in the HPV life cycle and cervical cancer development is different." (PMID 35408813, 2022). "A special case is represented by the transcription factor YY1, which was found to interact with both DDX3X and DDX5 in cervical cancer, where it can act both as an oncosuppressor and an oncogene, depending on the subset of genes that are activated." (PMID 35954483, 2022). "There was a negative correlation between YY1 expression and E-cadherin expression, and positive correlation between YY1 expression and HVP16 E6 expression in cervical cancer tissues." (PMID 29470526, 2018). "Correlation analysis further revealed that the expression of YY1 in CSCC tissues was positively correlated with expression of HPV16 E6, suggesting that YY1 can promote the expression of HPV16 E6 in cervical cancer pathogenesis." (PMID 29470526, 2018). "The proteins YY-1 and CDK6 are upregulated in CIN 1 and cervical cancer, respectively, by miR-29a and miR-29b, showing a fine-tuning regulation in the cervical carcinoma progress." (PMID 26057746, 2015).